KSR1 (kinase suppressor of ras 1)
Diseases named in the same sentence as KSR1 in open-access papers (continued):
Sharing a sentence is not in itself a finding about the gene and the disease.
cancer (30 papers, 2011 to 2026). A tumor composed of atypical neoplastic, often pleomorphic cells that invade other tissues. "Depleting KSR1 caused cancer cells to generate less EPSTI1 and to share more features with healthy cells, such as higher levels of E-cadherin on their surface and reduced mobility." (PMID 33970103, 2021). "Mediators of EMT- like phenotype activate cap-dependent translation initiation have been associated with increased aggressiveness and metastases of cancer cells, and we have shown that KSR1 can affect translation initiation." (PMID 33970103, 2021). "Loss-of-function studies in various cancer contexts further support KSR1′s tumor-promoting role." (PMID 41155983, 2025). "Its importance was most notable in Caenorhabditis elegans development as well as immune and cancer cells since in vivo models deficient in KSR-1 exhibited deficiencies in ERK activation in a stimulus-specific manner, resulting in resistance to inflammatory diseases and Ras-mediated cancers." (PMID 26973524, 2016). "Although it is theoretically possible to boost KSR’s activity in cancer via, for example, delivering a viral vector expressing KSR1, targeted activation of KSR1 remains technically challenging and untested in cancer." (PMID 41155983, 2025). "Emerging evidence indicates that KSR1 overexpression promotes cancer cell proliferation and survival, while genetic or pharmacologic inhibition of KSR1 attenuates RAS/MAPK signaling and suppresses tumor growth in preclinical models." (PMID 41155983, 2025). "Most of these KSR1 functions facilitate RAS transformation, and KSR1 has become a plausible drug target for combating RAS-driven cancers." (PMID 37511580, 2023). "A protein called KSR1 is a key component of a signaling pathway that is responsible for generating the proteins colon cancer cells need to survive." (PMID 33970103, 2021). "RNAi and small molecule screens using KSR1 as a reference standard have the potential to expose and target vulnerabilities in cancer." (PMID 29026529, 2017). "Targeting KSR1 in cancer using small molecule inhibitors has potential for therapy with reduced toxicity to the patient." (PMID 29026529, 2017). "The scaffold proteins of the Ras/MAPK pathway, including IQGAP1, KSR1, and Sur8, have essential roles in growth, transformation, and migration of cancer cells." (PMID 29383184, 2017). "A better understanding of the molecular determinants of the distinctive behaviour of KSR1 in different types of cancer is essential to the optimal targeting of this dual functional kinase-scaffold protein." (PMID 26425651, 2015). "In light of its regulatory role in oncogenic Ras-RAF-MAPKs signaling, extensive efforts have attempted to establish KSR1 as an oncogene in Ras-dependent cancers." (PMID 26425651, 2015). "Although clinical trials targeting KSR1 have yet to be initiated, clinical studies to target the RAS/MAPK signaling cascade at multiple levels in various cancers could inform the therapeutic effect of targeting KSR1 in human cancers, including HCC." (PMID 41155983, 2025). "Moreover, in addition to the role of KSR1 itself to RAS-mediated oncogenesis and its potential as a novel anti-cancer target, sphingolipid dysregulation has been linked to several cardiovascular, metabolic, and neurodegenerative diseases." (PMID 38474242, 2024). "Indeed, our data show that high KSR1 expression levels reduces the efficacy of the KRASG12C inhibitor sotorasib in human cancer cells." (PMID 35313064, 2022). "Adding EPSTI1 to the cancer cells that lacked KSR1 restored the traits associated with metastasis, such as high levels of N-cadherin, and allowed the cells to move more easily." (PMID 33970103, 2021). "It was found that PJA2 is able to ubiquitylate KSR1 to regulate the growth of cancer cells." (PMID 34372882, 2021).
cancer (continued). "KSR1 was upregulated in GC cancer compared with para-carcinoma tissues." (PMID 33461174, 2021). "EPHB4 was concluded to be functionally similar to KSR1 and might be targeted successfully in a cancer-specific manner." (PMID 33120942, 2020). "Kinase suppressor of Ras1 (KSR1) is involved in the control of both pro-coagulant and aggressive phenotypes of cancer cells by up-regulation of TF downstream of Erb (EGFR) oncogenes, and the use of KSR1 targeting agents is being explored as a therapeutic strategy." (PMID 24212618, 2011). "We also show that increased expression levels of KSR1 decrease the responsiveness to the KRASG12C inhibitor sotorasib in human cancer cell lines, thus suggesting that increased levels of expression of KSR may make tumour cells less dependent on KRAS oncogenic signalling." (PMID 35313064, 2022). "Therefore, targeting KSR1 or functionally similar proteins could be lethal to Ras-driven cancer cells with reduced toxicity to normal cells." (PMID 33120942, 2020). "We observed a weak, but statistically significant, positive correlation between KSR1 and YAP mRNA from 10,967 patient samples across all cancer types, supporting a functional correlation between KSR1 and YAP in malignancy." (PMID 41326667, 2025). "In particular, kinase suppressor of Ras 1 (KSR1) has emerged as a key modulator of RAS/MAPK signaling and a novel therapeutic target for cancer with pathway activation." (PMID 41155983, 2025). "Kinase Suppressor of RAS 1 (KSR1) is a scaffolding protein for the RAS-RAF-MEK-ERK pathway, which is one of the most frequently altered pathways in human cancers." (PMID 37511580, 2023). "To further assess this concept, we analyzed the expression of both KSR1 and IQGAP1 transcripts in a number of publicly available transcriptomal datasets present in both the Pan-Cancer and Gene Expression Omnibus (GEO) repositories." (PMID 36791195, 2023). "Trametinib derives its clinical anti-cancer efficacy from promoting the interaction of its primary targets MEK1/2 with KSR1/2, but has low affinity for KSR1 or KSR2 alone, meaning this interaction was missed during clinical development." (PMID 38049406, 2023). "While efficient ATP binding of KSR1 is required for the induction of RAS‐independent proliferation in MEFs, it seems to be less relevant for the reduced response to KRAS inhibitors in cancer." (PMID 35313064, 2022). "We found that seven genes (ADPRH, IL1R1, KSR1, SOCS2, JAK1, NFAT5, and SSH1) were more highly expressed in the lower-TMB subtype than in the higher-TMB subtype of more than 10 cancer types." (PMID 30634925, 2019). "In addition, Neilsen BL reported that KSR1 could be a therapeutic target for Ras-dependent cancers." (PMID 30832724, 2019). "Because KSR1 promotes Ras and ERK activation and yet is dispensable for normal development, its potential as a therapeutic target for Ras-driven cancers is being widely investigated." (PMID 30917119, 2019). "Using a reference standard, in this case KSR1, that is required for the survival and transformed properties of tumor cells but not non-transformed cells from the cognate tissue of origin allows FUSION to specifically detect cancer-specific targets." (PMID 33120942, 2020). "Although KSR1 is present both in non-transformed and transformed cells, KSR1 is essential to oncogenic Ras-driven cancers." (PMID 33120942, 2020). "To test the possibility that a different cancer genetic signature emerged in the absence of KSR1, we compared gene expression by RNA sequencing (RNASeq)." (PMID 29596465, 2018). "Moreover, we implicate several of these gene hits not only in ccRCC for the first time (BHLHB3, CAMK1, CDH13, ENPP3, KCNJ2, KSR1, PLOD2, and TCF8), but also in a cancer model for the first time (CEP290, EFCAB3, PGBD5, RAPGEF5, SSPN, and TOX2)." (PMID 24979721, 2014). "While this protection may not be complete in all cancer types, it has sparked substantial interest in finding out more about KSR1 functions in oncogenic transformation." (PMID 37511580, 2023).
cancer (continued). "It is tempting to speculate that certain pathophysiological conditions (e.g., carcinoma) may dissociate calmodulin from KSR1, enabling KSR1 to scaffold and activate MAPK in the absence of EGF or possibly other activators." (PMID 33766558, 2021).
tumor (22 papers, 2004 to 2025). "Endogenous IQGAP1 and KSR1 also associated with each other in the tumor cell lines of thyroid origin Cal62 and Hth83, demonstrating that this interaction is widespread among different types of cells." (PMID 36791195, 2023). "The activity of the E3 ubiquitin ligase complex, CRL4-DCAF1, and the Raf/MEK/ERK scaffold protein Kinase suppressor of Ras 1 (KSR1) are upregulated in Merlin-deficient tumours, which drives tumour growth." (PMID 32629964, 2020). "Remarkably, however, the KSR1−/− mice were significantly less susceptible to developing mammary tumours when crossed to a transgenic tumour-prone strain." (PMID 14735164, 2004). "It is possible that the loss of KSR1 in the stromal or immune compartment could have compensated for the loss of KSR1 in tumor cells, or that KSR1 deletion caused developmental changes which circumvented KSR1 dependence for tumors in this particular model." (PMID 29596465, 2018). "This was also the case, when comparing KSR1 levels in the primary tumor versus metastasis in samples coming from the same patient." (PMID 39263917, 2025). "To this end, we ectopically expressed KSR1 or KSR1F701A proteins in human tumour cells known to express the KRASG12C oncoprotein including MIA PaCa‐2 cells as well as two cell lines derived from PDX established from lung tumours, PDX‐dc1 and PDX‐dc1." (PMID 35313064, 2022). "This tumor-specific, KSR1-dependent regulation of mRNA translation of a subset of genes was predicted to selectively promote survival of CRC cells but not normal colon epithelia." (PMID 33970103, 2021). "Determining how KSR1- and ERK-dependent signaling promotes EPSTI1 translation should yield novel mechanisms underlying tumor cell metastatic behavior." (PMID 33970103, 2021). "The results showed that the average expression levels of KSR1 were significantly higher in tumor tissues than those in the normal tissues." (PMID 26673620, 2016). "Taken together, these results suggest that miR-497 inhibits tumor growth and angiogenesis with decreased KSR1 expression in vivo." (PMID 26673620, 2016). "MiR-497 acts as a tumor suppressor to inhibit cell proliferation, migration, invasion, tumor growth and angiogenesis via targeting KSR1." (PMID 26673620, 2016). "Our studies suggest the tumor suppressive action of KSR1 and its clinical relevance in patient stratification, placing KSR1 in the major oncoprotein pathways." (PMID 26425651, 2015). "However, unlike BRAF-mutant cells, small interfering RNA (siRNA)–mediated KSR1/2 depletion in tumor cells harboring oncogenic RAS induced a potent apoptotic response, indicating that APS-2-79 was not efficiently inhibiting KSR activity." (PMID 36791195, 2023). "Immunohistochemical scores were scored in accordance with the percentage of positive cells under the microscope and the intensity of staining, and the results showed that the scores of KSR1 in tumor tissues were higher than the scores of KSR1 in adjacent tissues." (PMID 35418575, 2022). "Further experiments support a tumor suppressive role of KSR1." (PMID 26425651, 2015). "As KISS1R, KSR1, CAMK1, and SSPN have been either previously implicated in tumor cell migration or are known to participate in extracellular matrix adhesion, we wanted to explore whether any of these factors mediate RCC cell invasiveness." (PMID 24979721, 2014). "In consonance, our results point to KSR1 as a critical orchestrator of cellular migration, in full agreement with previous findings which implicate KSR1 in the regulation of the actin cytoskeleton and, consequently, in the control of cell motility with pathological connotations in tumor cells." (PMID 39263917, 2025). "Given that Raf, Raf and KSR1 activities were not directly affected by the loss TPL2 kinase activity in IKKɛ-deficient tumor cells, there may be other mechanisms for the inhibition of canonical Ras/RAF/MAPK activation." (PMID 35391917, 2022).
tumor (continued). "KSR1, a scaffolding protein in the MAPK signaling cascade, plays a critical role in Ras-driven tumor proliferation." (PMID 40941703, 2025). "As in the case of KSR1, IQGAP1 depletion or blockade of its scaffold functions prevents RAS-ERK pathway–driven neoplasia." (PMID 36791195, 2023). "It was found that compared with sh-NC + oe-NC group, the volume and weight of transplanted tumor in sh-ELK4 + oe-NC group were reduced; compared with sh-ELK4 + oe-NC group, the tumor volume and weight were increased in sh-ELK4 + oe-KSR1 group." (PMID 34372882, 2021). "Upon removal of KSR1 or EPSTI1, the tumor cells switch back from highly migratory and invasive EMT-like state to the epithelial state." (PMID 33970103, 2021). "Further characterization of KSR1, EPSTI1 and the additional effectors repurposed by dysregulated translation in CRC should reveal additional novel mechanisms critical to CRC tumor survival and progression." (PMID 33970103, 2021). "KSR1 disruption inhibits HCT116 cell anchorage-independent growth in vitro and tumor formation in vivo." (PMID 33970103, 2021). "Since the efficacy of KSR1 knockdown with antisense oligonucleotides correlates with cellular uptake and not with plasma levels, the effect of antisense oligonucleotides may have been greater in certain cells, including tumor cells, compared with other tissues, such as the immune compartment." (PMID 29596465, 2018). "Consistent with in vitro data, levels of KSR1 and p-ERK1/2 in tumor tissues from miR-497 overexpression group were much lower than those of miR-NC group analyzed by immunoblotting assay." (PMID 26673620, 2016). "KSR1 protein is overexpressed in RCC in stage II-IV and metastatic samples, and demonstrates a cytoplasmic pattern of staining in both tumor and normal samples." (PMID 24979721, 2014). "Of these, we further establish a role for CDH13 in tumor angiogenesis, as well as a pro-migratory role for four novel factors including KISS1R, KSR1, CAMK1, and SSPN in ccRCC." (PMID 24979721, 2014). "We demonstrated previously that Kinase Suppressor of Ras 1 (KSR1), a molecular scaffold for the Raf/MEK/ERK kinase cascade, is required to maintain the transformed phenotype of Ras-driven tumor cell lines, but is dispensable for the survival and proliferation of non-transformed cells." (PMID 29491475, 2018). "In all, there were no obvious differences in early tumor development in Ksr1-/- mice compared to control animals in this PDAC model." (PMID 29596465, 2018). "We further confirmed with RT-qPCR that relative KSR2 expression did not increase in Ksr1-/- compared to Ksr1+/+ tumor samples, and so a compensatory role for KSR2 is less likely." (PMID 29596465, 2018). "The requirement for KSR1 in Ras-driven tumor formation, but not normal development, reveals KSR1 as a potential target for therapeutic intervention." (PMID 29026529, 2017). "First, absence of KSR1 inhibits tumor formation in different Ras-mediated mouse models (KSR1−/−), suggesting that KSR1 is required for Ras-transduced MAPK activated tumorigenesis." (PMID 26425651, 2015).
infection (3 papers, 2013 to 2022). The state of being infected such as from the introduction of a foreign agent such as serum, vaccine, antigenic substance or organism. "For instance, Kinase Suppressor of Ras 1 (KSR1) was upregulated following infection, and KSR1 encodes for a scaffolding protein which can localize to the plasma membrane and complex with B-Raf and MEK, promoting the phosphorylation of Rafs and activation of ERK1 and ERK2." (PMID 31561471, 2019). "This dose of infection did not induce any lethality, and bacterial clearance was similar between wild-type and KSR1-deficient mice (data not shown)." (PMID 23431403, 2013). "However, we could not detect any difference in the number and quality of the LCMV-specific memory CD8+ T cells in KSR1-/- mice 30 days after infection." (PMID 23431403, 2013). "To do so, we infected wild-type and KSR1-/- mice with recombinant Listeria monocytogenes expressing OVA (Lm-OVA), and analyzed the number and phenotype of OVA-specific CD8+ T cells by flow cytometry at different time points after infection." (PMID 23431403, 2013). "Furthermore, upon reinfection with Lm-OVA 30 days after the primary infection, OVA-specific CD8+ T cells expanded normally in KSR1-/- mice, confirming that there is no defect in CD8+ T cell memory cells in KSR1-/- mice." (PMID 23431403, 2013).
KSR1 also shares sentences with these, for which no sentence is quoted: metabolic disorders (3 papers); cardiac hypertrophy (2); -dependent (1); acute promyelocytic leukemia (1); colitis (1); complication (1); deafness (1); diabetic nephropathy (1); diabetic retinopathy (1); dyslipidemia (1); genetic disorders (1); Hypertension (1); hypogonadism (1); lung adenocarcinoma (1); lymphoma (1); neurodegenerative disease (1); oligoarticular JIA (1); ovarian carcinoma (1); polyarticular JIA (1); prostate carcinoma (1); rheumatoid arthritis (1); sarcoma (1); stomach cancer (1); type 2 diabetes mellitus (1).